LINC02542 (long independently transcribed non-coding RNA 2542)
Gene: Long non-coding RNA gene on chromosome 6 (81,843,774 to 82,169,391, reverse strand). Ensembl gene ENSG00000226453.
Diseases named in the same sentence as LINC02542 in open-access papers:
LINC02542 is named in the same sentence as 1 disease in open-access papers, as found by Europe PMC text mining. Sharing a sentence is not in itself a finding about the gene and the disease. The quoted sentences say what the papers report.
tumor (1 paper, 2022). "Interestingly, qRT-PCR results indicated that the expression of AP001619.1, AC020917.2, LINC01252, AC010789.2, AL356804.1, ZFHX2-AS1, AC002066.1, and AC008752.2, AC012313.5 was significantly higher in normal tissue while expression of LINC02542 was similar between normal and tumor tissue." (PMID 35965536, 2022).